IL18 (interleukin 18)
Diseases named in the same sentence as IL18 in open-access papers (continued):
Sharing a sentence is not in itself a finding about the gene and the disease.
sporotrichosis (1 paper, 2025). The commonest and least serious of the deep mycoses, characterized by nodular lesions of the cutaneous and subcutaneous tissues. "To verify the effect of IL-18 on sporotrichosis caused by S. globosa, we first determined its local expression in lesional skin of patients." (PMID 40489556, 2025). "This study unveils the dual role of IL-18 in human sporotrichosis caused by S. globosa—amplifying both Th1 and Th2 responses but ultimately driving pathogenic Th2 polarization through IL-2 crosstalk." (PMID 40489556, 2025). "Thus, there remains a gap in our understanding regarding the detailed roles of IL-18 in sporotrichosis patients, especially caused by S. globosa infection." (PMID 40489556, 2025). "To elucidate these questions, we investigated the in situ immune profile of skin lesions of patients and attempted to figure out the modulatory role of IL-18 in T cell responses against S. globosa infection and its impact on the progression of sporotrichosis." (PMID 40489556, 2025). "While prior studies indicate lymphocyte-derived IL-18, our analysis revealed that most of IL-18-expressing cells in sporotrichosis dermis exhibited atypical lymphocyte morphology, displaying larger cell bodies and irregular dendritic processes." (PMID 40489556, 2025). "Here we observed IL-18 in sporotrichosis lesions was positively correlated with both local expression of IL-4 and IFN-γ." (PMID 40489556, 2025). "To identify the cells secreting IL-18 in lesional skin, we performed multiple IHC (mIHC) staining on biopsies from sporotrichosis patients and HCs." (PMID 40489556, 2025). "Compared with HCs, the mRNA levels of IL-18 and its receptor (IL-18R) were both significantly elevated in all biopsies of sporotrichosis patients." (PMID 40489556, 2025). "qPCR, western blot, and IHC/mIHC were employed to profile IL-18, IL-18 BP, caspase-1 and IL-18R axis, along with Th1,Th2, and Th17 cells and their specific cytokines in sporotrichosis lesions versus healthy skin." (PMID 40489556, 2025). "In contrast, the expression level of pro-IL-18 in sporotrichosis skin lesions remained comparable to that observed in normal skin tissues." (PMID 40489556, 2025). "Our data showed a significant upregulation of IL-18 expression in sporotrichosis skin lesions compared to normal skin." (PMID 40489556, 2025). "Remarkably, only a single 24-kDa band was detected in normal skin lysates, but in the lysates from sporotrichosis skin lesions, most of the immunoreactive IL-18 protein showed a molecular weight of 18 kDa, with a weak positive signal at the position of 24 kDa." (PMID 40489556, 2025). "Our study significantly advances the understanding of regulatory effects of IL-18 on T cell-mediated immunity and the pathogenesis of sporotrichosis." (PMID 40489556, 2025). "Our study aims to characterize the T cell immune profile within skin lesions of sporotrichosis patients and to elucidate the role of IL-18 in modulating local immune responses against S. globosa infection, as well as its impact on disease progression." (PMID 40489556, 2025). "We found that IL-18R was elevated in the lesional skin and S. globosa-infected CD4+T cells in this study, particularly within the Th2 subset; however, whether IL-9 sensitizes Th2 cells to IL-18 signals in sporotrichosis needs further investigation." (PMID 40489556, 2025). "Notably, both the precursor and mature forms of IL-18 were detected in sporotrichosis lesions, with the mature form being predominant." (PMID 40489556, 2025).
squamous cell carcinoma (1 paper, 2020). A carcinoma arising from squamous epithelial cells. "Tgfbr1 and Pten were able to inhibit the expression of NLRP3, ASC, caspase-1, IL-1β, and IL-18 in a mouse squamous cell carcinoma of the head and neck model." (PMID 32723297, 2020).
staphylococcus aureus infection (1 paper, 2025). An infectious process in which the bacteria Staphylococcus aureus is present. "WikiPathways analysis emphasized high enrichment scores in IL-18 signaling pathway, aryl hydrocarbon receptor pathway, T-cell antigen receptor pathway during staphylococcus aureus infection, and Th17 cell differentiation pathway." (PMID 41333466, 2025).
streptococcal infection (1 paper, 2018). Any of the several infectious disorders caused by members of streptococcus, a genus of gram positive bacteria belonging to the family Streptococcaceae. "In fact, it has been shown that IL-18 can protect from Streptococcal infections independently of IFNγ." (PMID 29791511, 2018).
Streptococcus pneumoniae (1 paper, 2017). "Surprisingly, despite reduced pro-inflammatory cytokines, including IL-18, POP2TG mice displayed increased IFN-γ levels, which protected from Francisella tularensis and Streptococcus pneumoniae infection." (PMID 28580931, 2017).
stress-related disorder (1 paper, 2022). Stress-related disorders are mental health disorders that are a result of an atypical response to both short and long-term anxiety due to physical, mental, or emotional stress. "Moreover, our study suggests that IL18 may be a therapeutic target for psychiatric disorders, including stress-related disorders, although further clarification of its potential regulatory mechanism is required." (PMID 36151082, 2022).
sweet syndrome (1 paper, 2017). "We analyzed the circulating levels of interleukin-1β, interleukin-6, interleukin-18, neopterin, and soluble tumor necrosis factor receptors I and II, in order to clarify the pathogenesis of Sweet’s syndrome." (PMID 28668093, 2017).
Takayasu arteritis (1 paper, 2021). A rare inflammatory large-vessel vasculitis primarily affecting the aorta and its major branches, but also other large vessels, causing stenosis, occlusion, or aneurysm. "Takayasu Arteritis (TA) is a rare granulomatous, chronic large-vessel vasculitis that involves mostly the aorta and its major branches, and it is associated with increased expression of IL-8, IL-12, IL-17, IL-18 or IFN-alfa." (PMID 34394103, 2021).
thymic carcinoma (1 paper, 2025). Thymic carcinoma (TC) is a type of thymic epithelial neoplasm characterized by a high malignant potential. "Serum IL-18 levels were elevated—particularly in thymic carcinoma—and correlated with higher concentrations of type 2 cytokines (IL-4, IL-5, IL-9, IL-13)." (PMID 41368637, 2025).
thymus atrophy (1 paper, 2024). Acquired diminution of the size of the thymus associated with wasting as from death and reabsorbtion of cells, diminished cellular proliferation, decreased cellular volume, pressure, ischemia, malnutrition, reduced function or malfunction, or hormonal changes. "In accordance with the in vivo results, the effect of single treatments with TL1A and IL-18 was limited, while the combination of TL1A + IL-18 resulted in a profound loss of T cells, reflecting thymic atrophy." (PMID 38839915, 2024). "In vivo administration of TL1A and IL-18 induced acute thymic atrophy, while thymic neutrophils expanded." (PMID 38839915, 2024). "Our data suggest that TL1A and IL-18 are possible targets for preventing thymic atrophy and restoring normal thymic function." (PMID 38839915, 2024). "Collectively, our findings revealed a synergistic effect between TL1A and IL-18 in triggering acute thymic atrophy in vivo and thymic neutrophil expansion ex vivo." (PMID 38839915, 2024). "Combined administration of TL1A + IL-18 resulted in acute thymic atrophy and growth retardation, compared to the individual treatments, suggesting a synergistic effect." (PMID 38839915, 2024). "In this report, we document that TL1A and IL-18 synergistically induce acute thymic atrophy in vivo and ex vivo, accompanied by thymic neutrophil expansion." (PMID 38839915, 2024). "Taken together, our findings reveal that TL1A and IL-18 synergism induce acute thymus atrophy while promoting extramedullary thymic granulopoiesis in a NOTCH and GM-CSF-controlled manner." (PMID 38839915, 2024). "Additionally, when we examined the NTOC lobes using transmission electron microscopy (TEM), we observed marked morphological differences in the medulla corresponding to the TL1A + IL-18-induced thymic atrophy described by flow cytometry." (PMID 38839915, 2024).
tibia fracture (1 paper, 2010). Traumatic or pathological injury to the tibia in which the continuity of the bone is broken. "Nonetheless, the involvement of caspase-1 in complex regional pain syndrome triggered by tibia fracture seems to be dependent on IL-18 processing." (PMID 20920345, 2010).
tongue cancer (1 paper, 2015). A malignant neoplasm affecting the tongue. "In the present study, we assessed the effects of IL-18 expression on the regulation of TSCC cell viability and apoptosis and then explored the underlying molecular events, which may in turn provide a molecular basis for applying IL-18 as a novel agent for the clinical treatment of tongue cancer." (PMID 25591548, 2015). "To further verify the inhibitory effect of activated GSK-3β on tongue cancer, we used the selective GSK-3β inhibitor kenpaullone (KP) to treat IL-18-transfected CRL1623 cells and found that KP reduced GSK-3β phosphorylation and its activation, in turn inhibiting the activity of caspase-3 and -7." (PMID 25591548, 2015).
tuberous sclerosis (1 paper, 2016). Hereditary disease characterized by seizures, intellectual disability, developmental delay, and skin and ocular lesions. "Furthermore, we investigated the expression of IL-18 in the brain sections obtained from individuals affected by tuberous sclerosis with autistic behavior, mimicking different features of ASD subjects or by inflammatory diseases, compared to normal subjects." (PMID 26728085, 2016).
tubular adenocarcinoma (1 paper, 2025). An infiltrating adenocarcinoma in which the malignant cells form tubular structures. "The IL‐18/IL‐18BP ratio was significantly higher in the tubular carcinoma and PDAC cases compared to the intestinal‐type carcinomas." (PMID 39969214, 2025). "Our results support the hypothesis that some gastric IPMNs can progress to tubular adenocarcinoma through pancreatobiliary morphology with IL‐18‐driven immunosuppression as a possible mechanism for this progression." (PMID 39969214, 2025).
tubulointerstitial nephritis (1 paper, 2022). "In HK-2 cells, IL-18 knockdown attenuated necroptosis, transdifferentiating and fibrosis.In patients with tubulointerstitial nephritis, IL-18 protein expression was increased on renal biopsies using immunohistochemistry." (PMID 36379914, 2022).
type 2 diabetic nephropathy (1 paper, 2017). "Our previous studies identified NAP and six urinary markers, including three tubular markers (KIM-1, NGAL, and L-FABP), two pro-inflammatory markers (IL-18 and YKL-40), and a marker of intrarenal RAS status (angiotensinogen), as biomarkers for the early detection of type 2 diabetic nephropathy." (PMID 28912839, 2017).
vascular occlusion (1 paper, 2023). "The fact that IL-18 was also higher in VOC underlines the notion that this is not a classically inflammatory cytokine and supports previous indirect data hypothesizing the involvement of IL-18 in vascular occlusion in SCD." (PMID 36969226, 2023).
Ventriculomegaly (1 paper, 2008). An increase in size of the ventricular system of the brain. "In neonatal HPHC characterized by progressive ventriculomegaly and increased head circumference > P75, and control patients, this study aimed to determine and compare CSF IL18, IFNγ and sFasL concentrations." (PMID 19117508, 2008).
VEXAS syndrome (1 paper, 2024). An adult-onset inflammatory disease that affects only males and is caused by somatic, not germline, mutations. "Unsupervised principal components analysis (PCA) separated patients with VEXAS syndrome from the other groups on dimension 2, driven by inflammatory cytokines (IL-6, IL-18), IL-1 receptor antagonist (IL-1RA) and myelomonocytic markers (calprotectin and galectin-3)." (PMID 38291039, 2024).
wheat allergy (1 paper, 2025). "There are two studies investigating IL-18 polymorphisms in wheat allergy." (PMID 40077585, 2025). "Another study examined the role of IL-18 genetics in developing wheat allergy among South Korean bakers." (PMID 40077585, 2025).
Wiskott-Aldrich syndrome (1 paper, 2021). Wiskott-Aldrich syndrome (WAS) is a primary immunodeficiency disease characterized by microthrombocytopenia, eczema, infections and an increased risk for autoimmune manifestations and malignancies. "Analysis of serum cytokine levels in Wiskott-Aldrich syndrome patients pre- and post- treatment reveals IL-18 as a stable and reliable marker of inflammation." (PMID 33448368, 2021).
tumor (961 papers, 2005 to 2026). "IL-18 exhibited dual roles, associating with both immune activation and favorable outcomes depending on tumor context." (PMID 41745410, 2026). "Although IL-18 signaling typically induces KIT expression to promote tumor growth, A2AR-deficient mature NK cells show reduced IL-18R1 and KIT expression, making them less susceptible to adenosine’s inhibitory effects." (PMID 40297580, 2025). "They found that only IL-18-armored CAR T-cell treatment induced tumor shrinkage, which was associated with improved survival." (PMID 41019052, 2025). "Non‐pathogenic E. coli displaying decoy‐resistant IL18 mutein boosts anti‐tumor and CAR NK cell responses." (PMID 40878391, 2025). "IL-15 shows potential in enhancing NK cell-mediated anti-tumor activity, while IL-18 is associated with poor survival outcomes due to its role in increasing immunosuppressive NK cells and upregulating PD-1 expression." (PMID 41169398, 2025). "In experimental MHC-I deficient tumor models NK cell dysfunction can be reversed by cytokines including (engineered) IL-2 and combinations of IL-12 and IL-18 which promotes tumor clearance." (PMID 40849493, 2025). "Pearson-r correlation between tumor volume and all immune signatures revealed significant association of higher IL-7 and IL-18 with reduced tumor growth." (PMID 40386779, 2025). "There had been a noteworthy positive correlation seen in the TUM district (tumor tissue) between the concentrations of IL-18 and traditional Th1-associated cytokines, such as IFNγ, TNF-α, and IL-12." (PMID 41179937, 2025). "Paradoxically, elevated IL-18 expression has been associated with increased tumour aggressiveness and metastatic potential in specific contexts, potentially through mechanisms involving immune escape facilitation." (PMID 40738927, 2025). "IL18 armoring, we performed another experiment in B7E3 tumor-bearing mice, comparing all three IL18-armored variants of m2G-T CAR T cells." (PMID 38745414, 2024). "IL-18 is essential for epithelial barrier repair and has potential anti-tumor effects, as evidenced by the fact that IL-18-deficient mice are more prone to tumor development after AOM−DSS treatment." (PMID 39456655, 2024). "The abnormal manifestation of IL‐18 is linked to the emergence and advancement of cancer, potentially affecting the biology of tumours by controlling immune responses and pathways related to cell growth." (PMID 39188114, 2024). "Recently, it has been documented that IL-18 is overexpressed in several cancers including PCa and it is associated with advanced tumor stage and metastasis." (PMID 39335188, 2024). "Various cytokines, including IL-2, IL-12, IL-15, IL-18, and IL-21, have been implicated in significantly enhancing NK cell yield and cytotoxic effects against tumor cells." (PMID 39633491, 2024). "We next evaluated the safety and impact on efficacy of the mouse versions of these IL18 variants in an immunocompetent mouse tumor model." (PMID 38745414, 2024). "Mice lacking the inflammasome adaptor protein PYCARD (ASC) and caspase-1 also displayed higher tumor prevalence compared to wild-type mice, and the increased tumor burden was associated with reduced levels of IL-1β and IL-18 at the tumor site." (PMID 38553639, 2024). "Inflammasomes are activated in tumor cells, tumor-associated macrophages, tumor-associated fibroblasts, and bone-marrow-derived suppressive cells, resulting in the secretion of IL-1β and IL-18 in the TME." (PMID 38473997, 2024). "The applied chemoimmunotherapy caused the highest inhibition of tumor growth in the group receiving DC/IL-15/IL-15Rα/TAg + DC/IL-18/TAg at the level of 72.4%." (PMID 37545526, 2023). "The pro-tumoral role of IL-18 seems also to be linked to its release from tumor cells, whereas its antitumoral role seems mainly be linked to its release from dendritic cells, therefore, shaping the immune response." (PMID 37298187, 2023).